CD4 (CD4 molecule)
Diseases named in the same sentence as CD4 in open-access papers (continued):
Sharing a sentence is not in itself a finding about the gene and the disease.
liver disease (continued). "IL-17+ T cells comprised 1–3% of the T cell infiltrate in inflammatory liver diseases and included both CD4 (Th17) and CD8 (Tc17) cells." (PMID 22796894, 2012). "HAART treatment not only decreases necrotic inflammation and progressive liver diseases but also reduces the replication of viruses in the liver and increases the CD4 count." (PMID 22509187, 2012). "Such a model accounts for improvements in liver disease which occurs after highly active antiretroviral therapy (HAART)-induced immune reconstitution, and lower CD4+ T cell counts being associated with worsened liver function." (PMID 22110611, 2011). "CD4+ CD25+ Foxp3 Treg cells contribute to the alleviation of inflammatory liver diseases." (PMID 40918132, 2025). "Furthermore, to interrogate the potential systemic role of Th17 cells, we performed a GSEA analysis on published bulk RNA-seq data from CD4+ T cells obtained from peripheral blood of patients with liver disease and healthy individuals." (PMID 40705454, 2025). "In addition, we investigated the differentiation status of CD8+ and CD4+ T cells across different liver disease stages." (PMID 41028194, 2025). "Because recruitment of Th1-polarised CD4 T cells to the liver has been also described for other severe liver diseases, such as autoimmune hepatitis, it may represent an important mechanism of aggravating liver diseases." (PMID 39980752, 2025). "Identification of risk factors (such as ART interruption, function impairment, low/undocumented CD4 + cell count), early diagnosis and treatment of co-infections and liver disease could improve outcomes." (PMID 38388345, 2024). "Additionally the hypersplenism often present in liver disease can produce quantitative reductions in circulating white blood cells, including CD4+ T cells required for the control of most fungal pathogens." (PMID 36983473, 2023). "HIV infection can cause CD4+ T cell reduction and dysfunction, making the infected human body vulnerable to HBV, subsequently damaging HBV clearance and ultimately aggravating the progression of liver disease." (PMID 35432386, 2022). "It is still unclear whether this correlation is due to immunosuppression or whether a low CD4 count is itself a marker of advanced liver disease, as portal hypertension induced by cirrhosis can result in a reduced number of CD4 via splenic sequestration." (PMID 35076514, 2022). "However, it has also been reported that CD4+ T-cell counts are low (<400 cells/mm3) in CVID patients with liver disease." (PMID 36341360, 2022). "Based on the hypothesis in this study, we thoroughly explored the hepatic barrier by using various liver disease models, and many other liver cells were also investigated including macrophages, B cells, CD4+ T cells, and CD8+ T cells." (PMID 34336855, 2021). "In this review, we summarize what has been discovered so far regarding the role of the different CD4+ T cell polarization states in the progression of two prominent and still different liver inflammatory diseases: non-alcoholic steatohepatitis (NASH) and autoimmune hepatitis (AIH)." (PMID 34463867, 2021). "Importantly, this correlation between marker expression and cytokine production is also validated in blood and intra-tissue CD4+ T cells from patients with inflammatory liver diseases." (PMID 31118448, 2019). "The influence of HIV on progression of HBV-related liver disease has been attributed to a number of mechanisms including direct infection of hepatic cells, indirectly through ARV hepatotoxicity, CD4 T cell depletion causing cytokine deregulation and inflammation and/or impaired T cell response." (PMID 31752729, 2019). "In sum, lower CD4+ T and NK cells, as well as a decreased NK functionality may represent ex vivo biological markers of advanced liver disease." (PMID 31536177, 2019). "Lower platelet counts in groups with CD4 nadir < 500 may also reflect liver disease in some subjects." (PMID 30315476, 2018).
liver disease (continued). "By contrast, CD4+CD25+Foxp3+Treg cells contribute to attenuation of liver inflammatory diseases." (PMID 28646856, 2017). "Moreover, excess production of these cytokines by activated monocytes/macrophages, NK cells, CD4+ and CD8+ T cells have been associated with MCMV-induced liver disease in immunodeficient mice." (PMID 22880122, 2012). "The increased CXCL12, HLECS+ lymphocytes, and CD4+ lymphocytes in the presence of active liver disease in 11 HIV-1 infected patients suggests a potential regulatory axis between the liver and hematopoietic tissue that may include additional unknown factors." (PMID 22363634, 2012). "Notably, chronic systemic inflammation caused by abnormal levels of CD4+T cells and NK cells in PsA patients promotes the occurrence and development of hepatic steatosis, especially NAFLD, and significantly increases the risk of advanced liver disease." (PMID 35935983, 2022). "Consequently, the liver might not only represent an additional site of T cell priming, but its unique environment might also predetermine the fate of CD4+ T effector cells during inflammatory liver disease." (PMID 34463867, 2021). "LSECs ability to stimulate a pro-inflammatory CD4+ Th17 cell expansion in CCl4 and their differential response to an acute bacterial challenge in the context of cirrhosis pointed to specific inflammatory modulating mechanisms in experimental models of liver disease." (PMID 32429209, 2020). "This may suggest that the decreased CD4 T cell counts were not a cause of fibrosis but rather a result of splenic sequestration of leukocytes due to portal hypertension." (PMID 31752729, 2019). "Additionally, co-infected patients had a lesser increase in CD4 counts, which might reflect advanced portal hypertension." (PMID 31467319, 2019). "Therefore, we examined liver disease-related factors in groups by CD4 nadir < 500 cells/μl." (PMID 30315476, 2018). "However, patients with liver disease, through splenic sequestration of lymphocyte, may lead to a discrepancy between absolute CD4+ T-cell counts and CD4+ T-cell percentage, obscuring the accurate interpretation of these values." (PMID 30192795, 2018). "In addition, expression of CD56 and CD57 were upregulated on CD8+ and to a lesser extent CD4+ T cells in patients with compensated and decompensated liver cirrhosis compared with healthy controls, indicative of higher activation and senescence with advanced liver disease severity." (PMID 41028194, 2025). "Taken together, with advanced liver disease, CD8+ and CD4+ T cells shift towards an activated and exhausted phenotype in compensated liver cirrhosis, whereas in the decompensated state, a loss of these markers is present." (PMID 41028194, 2025). "Recent studies have underscored the significance of CD4+/CD8+ TRMs in solid organ transplantation, particularly in modulating transplant immunity 9, 11 and influencing outcomes in various liver diseases 20-22." (PMID 39239518, 2024). "We compared clinical, functional and hemodynamic parameters, severity of liver disease [Child–Turcotte–Pugh (CTP) and Model for End-stage Liver Disease-Na (MELD-Na) scores], CD4 count and highly active antiretroviral therapy (HAART) administration." (PMID 37240531, 2023). "Concomitant CD4 cell count at NAE diagnosis had also been found to be a predictor of mortality in certain events, such as neoplastic and hepatic diseases." (PMID 28886092, 2017). "T lymphocyte subsets, including CD4+ and CD8+ T cells, play an important role in the pathogenesis of liver disease." (PMID 27770815, 2016). "Our data suggest that CD4+ T cells expressing CD161 are an important component of the inflammatory infiltrate in HCV and other inflammatory liver diseases." (PMID 23181064, 2012). "The depletion of CD4+ cells significantly reduced the effectiveness of immune-based therapies in murine HCC models, suggesting that pre-existing liver disease may influence the response to immunotherapy." (PMID 40881277, 2025).
liver disease (continued). "It is also possible that our findings related to CD4+ cell counts are at least partially a result of liver disease rather than being related to HIV specifically." (PMID 39656170, 2025). "In addition, with increasing liver disease severity and onset of cirrhosis, both CD8+ and CD4+ T cells showed a gradual incline of activation and exhaustion marker expression." (PMID 41028194, 2025). "Moreover, the numbers of PD-1 + CD4+ and CD8 + T cells increased with the progression of liver disease in the participants with T2D." (PMID 37735474, 2023). "A study found that PBC patients had significantly higher levels of RANK in cholangiocytes and RANKL in CD4, CD8, and CD19 cells surrounding bile ducts than those with other liver diseases, implying that the RANK-RANKL axis plays a role in the process of bile duct injury." (PMID 35884999, 2022). "Thus, we found an improvement at the end of follow-up in non-invasive markers of liver disease (liver stiffness, FIB-4, AST, ALT, and albumin) and a significant increase in CD4+ T-cells/mm3, improving the patient's health status." (PMID 33785040, 2021). "It is a great pity that we did not collect the data of CD4+ T cell count, which is a reliable marker for assessing liver disease progression." (PMID 33860053, 2021). "First, we compared the proportions of CD4+ T cells displaying a classical TN, TCM, TEM, and TEMRA phenotype between blood of healthy controls, and blood and liver from patients with inflammatory biliary and hepatic diseases." (PMID 31118448, 2019). "INR remain at greater risk for health complications and non-AIDS diseases including cardiovascular disease, liver disease, renal disease, and malignancies when compared to immune responders (IRs) in whom the CD4 T-cell counts are properly restored." (PMID 31658294, 2019). "The infiltration of CD4+ T lymphocytes increased in SH2 patients to 12 ± 3 cells/mm (p < 0.005) and decreased thereafter with the grade of liver disease, reaching 9 ± 1 cells/mm in SH3 patients (p < 0.05); 5 ± 1 cells/mm in cirrhotic patients and 6 ± 1 cells/mm in patients with HE." (PMID 29445232, 2018). "A parallel study from Egypt confirmed our results and described higher FOXP3+ cell numbers and higher FOXP3+/CD4+ ratios in the livers of pAIH compared to non-AIH liver diseases." (PMID 28700730, 2017). "Il27ra−/− mice developed severe liver disease that was prevented by depleting CD4+ T cells, but not CD8+ T cells." (PMID 27259855, 2016). "ART initiation, irrespective of CD4 count, is an effective strategy to slow liver disease progression and is consistent with current HIV treatment guideline recommendations." (PMID 27471521, 2016). "Many previous studies have focused on the alteration of immune responses in HIV/HBV patients with abnormal liver function and lower CD4 counts, however little is known about individuals with milder liver disease that have normal levels of ALT and higher CD4 counts." (PMID 23849342, 2013). "It remains unclear how HIV propagates HCV liver disease, but clinical evidence demonstrates that decreasing HIV viral replication and improving CD4+ T cell counts, improves markers of liver disease." (PMID 22110611, 2011). "The pathologic mechanism(s) underlying the accelerated liver disease associated with HCV during HIV co-infection are not clearly understood, but have been proposed to be due to a loss of HCV-specific CD4+ T cells." (PMID 22110611, 2011). "In this study, we provide a comprehensive characterization of CD4+ and CD8+ T cells from 72 patients with chronic hepatitis virus infection and alcohol-related liver disease (ARLD) across different stages to decipher immune compartment changes during the course of liver disease." (PMID 41028194, 2025).
liver disease (continued). "That is why CD4+ T cells are reported to be particularly numerous in periportal areas, while CTLs constitute the major cell type in the area of interface lymphocytic infiltration, and the ratio of CD4+ T cell to CTL in Con A-induced AIH mice model is higher than in other liver diseases." (PMID 35291566, 2022). "We determine that the PBMC DNA methylation characters of progression of liver disease (7888 CGs) and difference between LC and CHB (4325 CGs) remain significant after correction for HBV markers and PBMC cell type (CD4+ T cell, CD8+ T cells, B Cells, natural killer cells, monocytes, granulocytes)." (PMID 32513305, 2020). "Even if HCV treatment is not readily available across China, these patients could be prioritized for HIV treatment regardless of CD4 cell count because some studies have shown that liver disease improves with ART." (PMID 26979535, 2016). "The CD4/CD8 T cell ratio is 1:3.5 for the liver versus 2:1 for blood lymphocytes, suggesting that the intrahepatic CD4 + and CD8 + T cells may have a specialized role in the pathogenesis of liver disease through an immune response." (PMID 21851644, 2011). "While the percentages of CD57+ CD8 T cells were significantly increased in patients with liver disease, as a single marker, it was not sufficient to distinguish patients with and without this manifestation and was inferior to the more established investigation of reduced naïve CD4 T cells." (PMID 40496855, 2025). "However, during the follow-up there was an increase in TEMRA CD4+ T cells (1.24 ± 1.16% vs. 2.14 ± 1.14%, p = 0.03) in patients with AC, and a decrease of Th17 cells (14.16% ± 4.31 vs. 12.35% ± 6.40, p = 0.03) in patients without liver disease." (PMID 39755990, 2025). "Although hyperbilirubinemia alone is not an exclusive symptom of liver diseases, its interpretation, together with other parameters, such as CD4+ levels, albumin levels, platelets, and elevated liver enzymes, could help healthcare professionals identify HIV patients at risk for liver complications." (PMID 38787212, 2024). "The reason for is; at very lower CD4 count (200 cells/μl), the course of HBV infection may be different from the immune-competent individuals, meaning the primary infection will be a mild liver disease with a lower incidence of icteric and lower rates of spontaneous clearance of HBV." (PMID 26855663, 2016). "HIV can directly infect cells of the liver and HIV-mediated depletion of CD4+ T-cells in the gastrointestinal tract (GI tract) results in increased circulating lipopolysaccharide (LPS), both of which may impact on TLR signaling in the liver and subsequent liver disease progression." (PMID 22474436, 2012). "SepSecS-specific CD4+ T cell clones were found in patients with AIH who were anti-SLA-positive and anti-SLA-negative,and, to a lesser extent, in patients with non-AIH liver diseases and in healthy individuals." (PMID 39817450, 2025). "CD4+CD28−CD57+ and CD8+CD28−CD57+ T cells increased 2.9- and 1.3-fold, respectively (both p < 0.05), in T2DM individuals with NASH or cirrhosis vs. those without liver disease." (PMID 40362271, 2025). "Moreover, the transcription factor T-bet was elevated in CD8+ and CD4+ T cells from patients with compensated liver cirrhosis compared with healthy controls, and Eomes was slightly upregulated in CD8+ T cells but not CD4+ T cells from liver disease patients with absence of cirrhosis." (PMID 41028194, 2025).
Cryptococcal meningitis (135 papers, 2007 to 2026). Meningeal inflammation produced by cryptococcus neoformans, an encapsulated yeast that tends to infect individuals with acquired immunodeficiency syndrome and other immunocompromised states. "Independent risk factors for mortality in HIV-associated cryptococcal meningitis (HCM) include low CD4+ T cell counts, advanced age, and low body weight." (PMID 38613657, 2024). "Primary immunodeficiencies linked with cryptococcal meningitis primarily affect the crosstalk between CD4 T-cells and macrophages, such as loss-of-function mutations in IL12RB131 and GATA232." (PMID 37938547, 2023). "FTY in particular can be associated with cryptococcal meningitis, an infection described in other conditions which affect CD4 count such as HIV." (PMID 35028898, 2022). "Development of cryptococcal meningitis is largely seen in the context of CD4 T-cell deficiency, such as advanced HIV infection." (PMID 35186781, 2021). "A previous study of the global burden of HIV-associated cryptococcal meningitis estimated the overall prevalence of cryptococcal antigen in patients with CD4 cell counts < 100 cells/mm3 to be 6%." (PMID 33916153, 2021). "In this cohort of PLWH in sub-Saharan Africa, serum CrAg positivity was associated with increased risk of death or cryptococcal meningitis among participants with CD4 100–200 cells/mm3 as well as those with CD4 < 100 cells/mm3." (PMID 31959112, 2020). "One such study examined HIV+/cryptococcal meningitis+ patients and found that despite having higher CD4+ T cells, males had higher risk of death." (PMID 31477151, 2019). "Risk factors for mortality in patients with cryptococcal meningitis are: high CSF fungal load, CD4 count < 100 cells/μl, poor CSF inflammatory response (< 20 leukocytes/mm3), and delayed diagnosis and treatment." (PMID 30867046, 2019). "Pre-emptive treatment associated to ART adherence, viral suppression and CD4 restoration are main protective factors to avoid cryptococcal meningitis." (PMID 31344140, 2019). "Cryptococcal meningitis has emerged as a leading cause of death in individuals with impaired CD4 T cell-mediated immunity." (PMID 28334020, 2017). "Cryptococcal meningitis (CM) is a leading cause of death among HIV-infected patients with low CD4+ T-lymphocyte (CD4) counts." (PMID 27390864, 2016). "Research indicates that the spectrum of meningitis varies between countries: in parts of Africa and South East Asia, cryptococcal meningitis is the leading cause of adult meningitis, with most of the cases occurring in patients with CD4 counts <100 cells/mm3." (PMID 26491454, 2015). "By multivariate analysis, risk factors for cryptococcal meningitis included: CD4 counts of less than 100 cells/mm3 (OR 28.0, 95% CI 2.9-272.0), altered mental status (OR 25.3, 95% CI 5.1-126.2), neck stiffness (OR 10.2, 95% CI." (PMID 21988905, 2011). "Cryptococcal meningitis was associated with confusion, social withdrawal, seizures, fever, tachycardia, meningismus, oral candidiasis, and low Glasgow coma scales and CD4 count." (PMID 17493266, 2007). "Furthermore, a CD4 count <100 cells/μL is a major risk factor for the morbidity and mortality of cryptococcal meningitis." (PMID 41425969, 2025). "Additionally, three, we would argue that receiving ART at baseline (and subsequently higher CD4 counts) are in the causal pathway for CSF culture sterility in persons with cryptococcal meningitis." (PMID 36675867, 2022). "Therefore male patients are more likely to present with lower CD4 counts and are subsequently at high risk of cryptococcal meningitis." (PMID 27669564, 2016). "In a combined cohort of patients enrolled in clinical studies for HIV-associated cryptococcal meningitis in Thailand, Malawi, South Africa, and Uganda, the median baseline CD4 count was just 24 cells/μL (IQR 10–50 cells/μL), with similar CD4 counts observed in Botswana, Uganda [43••], and Vietnam." (PMID 27257597, 2016).